ANO1 (anoctamin 1)
Diseases named in the same sentence as ANO1 in open-access papers (continued):
Sharing a sentence is not in itself a finding about the gene and the disease.
glucose metabolic disorder (2 papers, 2020 to 2024). "Therefore, the knockdown of ANO1 can ameliorate obesity, hepatic glucose metabolism disorders, and steatosis caused by a high‐fat diet, and ANO1 may be a potential therapeutic target for NAFLD." (PMID 38685684, 2024). "In addition, ANO1 promotes hepatic steatosis, induces glucose metabolism disorders, and facilitates the development of NAFLD." (PMID 38685684, 2024).
Hepatic steatosis (2 papers, 2020 to 2024). Steatosis is a term used to denote lipid accumulation within hepatocytes. "Guo et al31 reported increased expression of ANO1 in the liver of mice and patients with hepatic steatosis." (PMID 38685684, 2024). "As the NAFLD score increased, the abundance of ANO1 in the liver also increased, suggesting that ANO1 may play a role in hepatic steatosis." (PMID 38685684, 2024).
Kidney Cyst (2 papers, 2016 to 2021). Abnormal fluid filled sac within the kidney, either acquired or congenital. "ANO1 is also expressed in Madin-Darby canine kidney (MDCK) epithelial cell line which is widely used for studying the growth of kidney cysts, which suggests a role in renal function." (PMID 26811235, 2016).
laryngeal tumors (2 papers, 2015 to 2021). "ANO1-positive expression was found at each anatomic site, although with a higher frequency in oropharyngeal and hypopharyngeal tumours compared to laryngeal tumours (P = 0.065)." (PMID 26498851, 2015). "Thus, patients with ANO1-positive oropharyngeal tumours exhibited a significantly improved disease-specific survival, compared to hypopharyngeal and laryngeal tumours." (PMID 26498851, 2015). "Thus, patients with ANO1-positive oropharyngeal tumours exhibited a significantly improved DSS and OS; whilst ANO1 expression showed no influence on survival of patients with hypopharyngeal, and was associated with a poorer survival, although not significant, in laryngeal tumours." (PMID 26498851, 2015).
leukaemia (2 papers, 2016 to 2020). "Importantly, ChIP-seq data assembled in the UCSC genome browser show Myc/Max binding near the promoter region of ANO1 in breast and leukaemia cells." (PMID 26837714, 2016).
metastasis (2 papers, 2018 to 2023). The spread or migration of cancer cells from one part of the body (where they first appeared) to another. "Expression of ANO1 was significantly associated with distant metastatic relapse (P < 0.001), latent bone metastasis (P = 0.011), and β-catenin expression (P = 0.002), cyclin D1 expression (P = 0.004), MMP expression (P = 0.023), and snail expression (P = 0.001)." (PMID 29416639, 2018). "In our results, ANO1 expression was significantly associated with latent metastasis (distant metastatic relapse; P < 0.001, latent bone metastasis; P = 0.011) of BCA, suggesting that ANO1 might be involved in the progression of cancer after initial treatment." (PMID 29416639, 2018).
metastatic prostate carcinoma (2 papers, 2017 to 2023). A carcinoma that arises from the prostate gland and has spread to other anatomic sites. "A significant reduction in proliferation, metastasis, and invasion of human metastatic prostate cancer PC-3 cells was observed after treatment with shRNA targeting human ANO1." (PMID 36674697, 2023). "ANO1 is the major CaCC in PC-3 cells and inhibition of ANO1 significantly decreases cell proliferation in human metastatic prostate cancer PC-3 cells." (PMID 28362855, 2017).
myocardial infarction (2 papers, 2023 to 2025). Gross necrosis of the myocardium, as a result of interruption of the blood supply to the area, as in coronary thrombosis. "But this study only used in vitro models of CFs and did not include in vivo experiments (e.g., animal models of myocardial infarction) to validate the pathological role of ANO1." (PMID 41210337, 2025).
neuropathic pain (2 papers, 2015 to 2021). Chronic pain caused by damage to nerve fibers. "Namely, the selective anoctamin-1 inhibitor T16Ainh-A01 was less effective than CaCCinh-A01, which inhibits anoctamin-1 and other CaCCs, suggesting that activation of other CaCCs besides anoctamin-1 contribute to inducing neuropathic pain." (PMID 26130088, 2015).
neuropathy (2 papers, 2014 to 2015). A disorder affecting the nervous system that manifests with pain, tingling, numbness, and/or muscle weakness. "In summary, the present study revealed that Ano1 deletion in DRG neurons reduced inflammation and neuropathy-induced hyperalgesia and allodynia." (PMID 24450308, 2014).
osteoporosis (2 papers, 2022 to 2023). A condition of reduced bone mass, with decreased cortical thickness and a decrease in the number and size of the trabeculae of cancellous bone (but normal chemical composition), resulting in increased fracture incidence. "Taken together, our findings established Ano1 as a player in the field of osteoclast biology, advancing our understanding of osteoporosis and osteopetrosis." (PMID 35610255, 2022). "The close relationship between ANO1 expression and function in osteoclasts prompted us to explore the pathological role of ANO1 in human osteoporosis." (PMID 35610255, 2022). "Ano1 levels were obviously elevated during osteoclastogenesis and in the bone tissues of osteoporosis patients, and were positively correlated with osteoclast activity." (PMID 35610255, 2022). "Anoctamin 1 protein levels are substantially increased in osteoporosis patients and this closely correlates with osteoclast activity." (PMID 35610255, 2022). "The protein level of ANO1 in osteoporosis patients (T ≤ −2.5) was significantly higher than that in non-osteoporosis patients (T > −2.5)." (PMID 35610255, 2022). "In the future, it will be better to use the osteoclast specific delivery strategy for the application of Ano1 inhibitor in osteoporosis treatment." (PMID 35610255, 2022). "An understanding of the expression and function of Ano1 in osteoclasts will allow the identification of a therapeutic target for osteoporosis or osteopetrosis patients." (PMID 35610255, 2022). "In individuals with osteoporosis, this makes ANO1 a viable therapeutic target." (PMID 36836529, 2023). "The unique molecular mechanism of Ano1, including Cl− channel activity and ability to physically interact with other proteins, contributes to its strong regulatory effects on osteoporosis and osteopetrosis and advances our understanding of bone metabolism related diseases." (PMID 35610255, 2022). "Finally, Anoctamin 1 deletion significantly alleviates ovariectomy induced osteoporosis." (PMID 35610255, 2022). "However, the role of Ano1 in osteoporosis and bone remodeling has been unknown." (PMID 35610255, 2022).
psoriasis (2 papers, 2021 to 2024). An autoimmune condition characterized by red, well-delineated plaques with silvery scales that are usually on the extensor surfaces and scalp. "Based on previous findings, we investigated whether ANO1 was associated with proliferation of keratinocytes and inflammation of the epidermis or development of psoriasis-like symptoms using an animal disease model." (PMID 34281197, 2021). "Identification of the effects of ANO1 on abnormal proliferation of keratinocytes, one of the main causes of psoriasis progression, will help illustrate the underlying mechanisms that induce psoriasis progression and develop drugs for treatment of psoriasis." (PMID 34281197, 2021). "Overexpression, gain of function, and activation of channels, including nAChR, TRPV1, TRPV3, TRPV4, TRPM4, and ANO1 in keratinocytes, as well as TRPV1, nAChR, Kv1.3, and KCa3.1 in immune cells, have been associated with the induction of psoriasis." (PMID 38474002, 2024). "Based on these results, these ANO1 inhibitors are good candidates to study keratinocyte hyperproliferation-related psoriasis." (PMID 34281197, 2021). "Based on these findings, we investigated the effects of ANO1 on HaCaT cell proliferation and psoriasis development in mouse skin." (PMID 34281197, 2021). "The expression of ANO1 mRNA was increased (p = 0.059, Student’s t-test) in psoriasis tissues compared to healthy tissues." (PMID 34281197, 2021). "In conclusion, we determined that ANO1 was expressed highly in HaCaT keratinocytes and the epidermal layer of patients with psoriasis." (PMID 34281197, 2021). "Coapplication of IMQ and T16Ainh-A01 on ears of mice reduced not only symptoms of IMQ-induced psoriasis such as thickening and erythema, but also expression of ANO1 and pERK1/2 compared to that of application of IMQ alone." (PMID 34281197, 2021). "Taken together, these results suggest that ANO1 inhibition alleviates the typical symptoms of psoriasis, thickening and erythema." (PMID 34281197, 2021). "To investigate whether pharmacological inhibition of ANO1 attenuates psoriasis-like symptoms in vivo, we applied IMQ cream and T16Ainh-A01, an ANO1 blocker, alone or together on the right ears of mice for seven consecutive days." (PMID 34281197, 2021). "Furthermore, we found that coapplication of IMQ and ANO1 inhibitors on the ears of mice reduced not only symptoms of IMQ-induced psoriasis, but also expression of ANO1 and phosphorylation of ERK1/2." (PMID 34281197, 2021). "To determine the role of ANO1 in psoriasis, we first investigated whether ANO1 was expressed in the HaCaT keratinocyte cell line or in human skin tissue." (PMID 34281197, 2021). "Based on previous studies alongside our result demonstrating that ANO1 promotes hyperproliferation of keratinocytes, we predicted that inhibition of ANO1 activity by the four compounds would indicate its crucial role in the pathophysiology of psoriasis." (PMID 34281197, 2021). "On the basis of these findings, we hypothesized that ANO1 induces abnormal proliferation of keratinocytes, followed by psoriasis progression." (PMID 34281197, 2021). "In addition, we distinguished the effects of ANO1 on psoriasis development and investigated ANO-related mechanisms underlying psoriasis development by inducing psoriasis-like symptoms in mouse ears using imiquimod (IMQ) cream." (PMID 34281197, 2021). "Therefore, considering keratinocytes are the most common cell type in the epidermis, it is believed that patients with psoriasis have a thicker epidermis composed of keratinocytes highly expressing ANO1 compared to normal subjects." (PMID 34281197, 2021). "In addition, we found that psoriasis tissue exhibited not only a thicker epidermis layer, but also stronger expression of ANO1 than normal tissue." (PMID 34281197, 2021). "Therefore, also considering the decrease in HaCaT pERK1/2 by ANO1 knock-down, ANO1 likely plays a pivotal role in the progress of psoriasis-like dermatitis through the ERK pathway." (PMID 34281197, 2021).
psoriasis (continued). "Assuming that psoriasis promotes expression of various proinflammatory cytokines including IL-23 and IL-17, we investigated the gene expression of cytokines and ANO1 in the right ears of control, IMQ, and IMQ + 100 μM A01 groups on the eighth day after application." (PMID 34281197, 2021). "In addition, expression of inflammation-related cytokines including IL-17, IL-6, and TNF-α upregulated by application of IMQ was decreased by ANO1 inhibition, showing that psoriasis-like inflammation is alleviated by inhibition of ANO1." (PMID 34281197, 2021). "Moreover, the expression levels of ANO1 protein in psoriasis tissues were also significantly higher than in normal tissues." (PMID 34281197, 2021). "Therefore, since these four compounds directly inhibit activity of the ANO1 channel, it is supposed that ANO1 may be related to psoriasis." (PMID 34281197, 2021).
rectal cancer (2 papers, 2022 to 2023). A primary or metastatic malignant neoplasm that affects the rectum. "In our study, CYP1B1, ANO1, and RIOK3 were negatively associated with prognosis and nCRT response in rectal cancer." (PMID 36505493, 2022).
schizophrenia (2 papers, 2019 to 2026). A major psychotic disorder characterized by abnormalities in the perception or expression of reality. "In this study, we demonstrate that developmental loss of ANO1 function in cholinergic neurons of the medial habenula (mHb) leads to behavioral and molecular alterations relevant to schizophrenia pathophysiology." (PMID 41527097, 2026). "Taken together, our study provides novel evidence that developmental ANO1 deficiency in mHb cholinergic neurons induces schizophrenia-relevant behavioral and molecular phenotypes." (PMID 41527097, 2026). "This suggests a critical developmental window during which ANO1 loss impacts dopaminergic circuitry relevant to schizophrenia-related phenotypes." (PMID 41527097, 2026). "Further research is warranted to clarify the causal relationships between ANO1 deficiency, thalamocortical dysfunction, and schizophrenia-like behaviors, and to explore whether pharmacological interventions can effectively normalize these alterations." (PMID 41527097, 2026). "Moreover, ANO1 cKO mice exhibited elevated Drd2 expression in the ventral medial geniculate nucleus (MGv) and transcriptomic alterations overlapping with schizophrenia-associated genes." (PMID 41527097, 2026). "Comparison of these differentially expressed genes with a curated list of schizophrenia-associated genes revealed that the overlapping 217 genes, as well as the ANO1 and GPR151 genes, exhibited marked differences in expression patterns in ANO1 cKO mice." (PMID 41527097, 2026). "To assess sensorimotor gating deficits, we performed pre-pulse inhibition (PPI) testing in ANO1 cKO mice, as impairments in PPI are commonly observed in schizophrenia models." (PMID 41527097, 2026).
Sepsis (2 papers, 2019 to 2022). Sepsis is defined as life-threatening organ dysfunction caused by a dysregulated host response to infection. "In addition, treatment targeting IL-17A also elevated the low mRNA expression levels of c-Kit and Ano-1, which are specific biomarkers that are expressed in ICCs and induced by sepsis." (PMID 31531179, 2019).
thyroid cancer (2 papers, 2019 to 2025). "Therefore, it is plausible that ANO1 downregulation could contribute to the molecular mechanisms underlying thyroid cancer dedifferentiation." (PMID 39982585, 2025). "Taken together, these results strongly suggest that the suppression of ANO1 activity inhibits the migration and invasion of human thyroid cancer cells." (PMID 31489251, 2019). "Therefore, the finding of ANO1 downregulation in thyroid cancers with low iodine avidity is plausible and may suggest that this gene constitutes a potentially important differentiation marker in subsets of thyroid neoplasia." (PMID 39982585, 2025).
thyroid tumor (2 papers, 2019 to 2025). A benign or malignant neoplasm affecting the thyroid gland. "However, only single studies have analyzed ANO1/DOG1 immunoreactivity in thyroid tumors." (PMID 39982585, 2025).
allergic rhinitis (1 paper, 2025). Inflammation of the nasal mucous membranes caused by an IgE-mediated response to external allergens. "Magnolol alleviates allergic rhinitis by inhibiting ANO1, reducing mucus secretion and inflammatory cytokine release." (PMID 40356890, 2025).
benign thyroid tumors (1 paper, 2019). "We examined ANO1 expression in patients with benign thyroid tumors, papillary thyroid carcinoma, and ATC." (PMID 31489251, 2019).
bone marrow hypoplasia (1 paper, 2019). "Since high dose 5-Aza-CdR has potential risk of leukopenia or bone marrow hypoplasia, targeted delivery of concentrated 5-Aza-CdR via advanced drug delivery system may more efficiently recover ductal ANO1 expression with minimal systemic toxicity." (PMID 31847128, 2019).
brain cancer (1 paper, 2022). A primary or metastatic malignant neoplasm affecting the brain. "TRPV4 is another potential binding partner for EGFR, ANO1, and IP3R, although this has yet to be demonstrated in brain cancer cells." (PMID 36497413, 2022).
coronary artery spasm (1 paper, 2025). "The pathophysiological mechanism underlying acidosis-induced coronary artery spasm may be associated with the enhanced activity of the TMEM16A/anoctamin 1 (ANO1), a CaCC, in coronary arterial smooth muscle cells." (PMID 40988207, 2025).
Encephalocele (1 paper, 2024). A neural tube defect characterized by sac-like protrusions of the brain and the membranes that cover it through openings in the skull. "We then did another genetic rescue experiment to prove that induction of the FGF genes—triggered by ectopic contacts with the distal putative Ano1 brain enhancers (ABEs)—results in encephalocele." (PMID 39372737, 2024). "Together, these data reveal that the loss of the C1-C4 boundary exposes the three FGF genes to brain enhancers of Ano1, which results in strong ectopic brain expression and encephalocele." (PMID 39372737, 2024). "Our data also provide important insight into potential congenital origins of encephalocele, and it will be important to investigate whether human encephalocele patients present sequence variants that may affect CTCF binding at the boundary between ANO1 and the FGF genes." (PMID 39372737, 2024).
endometrioid tumor (1 paper, 2019). A benign, borderline, or malignant epithelial tumor of the female reproductive system characterized by the presence of glands and/or cysts lined by neoplastic cells that resemble endometrial cells. "High Ano1 expression is essential for survival and its expression was altered in papillary serous tumor and endometrioid tumor compared with healthy endometrium." (PMID 30813939, 2019). "ANO1, SOX17, CGNL1, DACH1, RUNDC3B, SH3YL1 and CRISPLD1 were significantly downregulated both in papillary serous tumors and endometrioid tumor." (PMID 30813939, 2019).
Fanconi renotubular syndrome (1 paper, 2023). A genetic or acquired disorder characterized by impairment of the function of the proximal tubules of the kidney. "The renal manifestation of the child, which can be diagnosed as Fanconi renotubular syndrome, has an unknown cause but may result from the effect of the ANO1 gene." (PMID 37152320, 2023).
gallstones (1 paper, 2025). Solid crystalline precipitates in the biliary tract, usually formed in the gallbladder, resulting in the condition of cholelithiasis. "Dysfunctional ANO1 can impair bile secretion, promoting gallstone formation, suggesting its potential as a susceptibility gene for gallstones." (PMID 40356890, 2025).
glomerulosclerosis (1 paper, 2025). A hardening of the kidney glomerulus caused by scarring of the blood vessels. "Dysfunctional ClCs, including calcium-activated TMEM16A (ANO1) and volume-regulated VRAC (LRRC8), trigger NLRP3 inflammasome activation, excessive ROS production, and TGF-β/Smad-driven epithelial-mesenchymal transition (EMT), promoting glomerulosclerosis and interstitial fibrosis." (PMID 40641971, 2025).
intestinal dysmotility syndrome (1 paper, 2023). "Anoctamin 1 (ANO1)-related intestinal dysmotility syndrome (OMIM: 620045) is an extremely rare disorder with only 2 cases reported in the medical literature." (PMID 37200714, 2023).
laryngeal carcinoma (1 paper, 2015). Carcinoma that arises from the laryngeal epithelium. "We next studied the relationship of ANO1 protein expression and gene amplification with the risk of developing laryngeal cancer in patients with premalignant lesions." (PMID 26498851, 2015). "More importantly, ANO1 gene amplification but not ANO1 expression correlated almost significantly with increased laryngeal cancer risk." (PMID 26498851, 2015).
laryngeal epidermoid carcinoma (1 paper, 2010). "To investigate the effects of ANO1 overexpression on tumourigenesis, we used the human HEp-2 cell line, which was established from a laryngeal epidermoid carcinoma and expresses low levels of ANO1 compared with the other HNSCC cells lines that we tested (data not shown)." (PMID 20664600, 2010).
male infertility (1 paper, 2022). The inability of the male to effect fertilization of an ovum after a specified period of unprotected intercourse. "This is not surprising, as ANO1 also interacts with other genes that play a role in male infertility, and especially sperm motility and morphology." (PMID 36290414, 2022).